LPL (lipoprotein lipase)
Diseases named in the same sentence as LPL in open-access papers (continued):
Sharing a sentence is not in itself a finding about the gene and the disease.
hypertriglyceridemia (continued). "On the other hand, in SAT, AngII increases LPL activity to deposit TG effectively in the cells to prevent hypertriglyceridemia, probably independent of the feeding/fasting cycle." (PMID 26447765, 2015). "Increased levels of free fatty acids can decrease mRNA expression or activity of lipoprotein lipase (LPL) in adipose tissue and skeletal muscle, and increased synthesis of VLDL in the liver can inhibit lipolysis of chylomicrons, which promotes hypertriglyceridemia." (PMID 24733068, 2014). "Further, in diabetic state lipoprotein lipase is not initiated because of insulin inadequacy, stimulating hypertriglyceridemia." (PMID 25114914, 2014). "The hypertriglyceridemia of obesity and obesity-related insulin resistance is primarily due to an overproduction of VLDL, although at some level VLDL clearance decreases as tissue lipoprotein lipase (LPL) becomes saturated." (PMID 23434905, 2013). "In the absence of GPIHBP1, LPL is mislocalized to the subendothelial spaces, resulting in severe hypertriglyceridemia." (PMID 23186339, 2012). "As VLDLs in excess are not be fully metabolized by lipoprotein lipase, a state of a hypertriglyceridemia would occur." (PMID 22963080, 2012). "Our results clearly showed for the first time that hematopoietic cell-derived LPL alone was nearly sufficient to compensate for the lack of LPL in other tissues with regard to improving hypertriglyceridemia." (PMID 21980507, 2011). "Reduced LPL activity has been shown to lead to an inhibition in the lipolytic rate of the chylomicrons and the very-low-density lipoproteins (VLDL), triggering the development of hypertriglyceridaemia and the subsequent dyslipidaemia seen in the MetS." (PMID 20670429, 2010). "Congenital generalized lipodystrophy, presenting as an autosomal recessive condition with near-total systemic absence of adipose tissue, results in severe hypertriglyceridemia due to delayed TRL catabolism, primarily linked to profound insulin resistance and reduced LPL activity." (PMID 38841827, 2024). "Therefore, in this study, we investigate the frequency of LPL-Hind III and APO CII-Ava II polymorphism in patients with severe hypertriglyceridemia not suffering from any secondary cause, as well as a group of normotriglyceridemia subjects." (PMID 37954769, 2023). "Increased levels of free fatty acids can decrease mRNA expression or activity of lipoprotein lipase (LPL) in adipose tissue and skeletal muscle, and the increased synthesis of VLDL in the liver can inhibit the lipolysis of chylomicrons, which promotes hypertriglyceridemia." (PMID 37887147, 2023). "Elevated plasma TGs (hypertriglyceridemia) results from an imbalance between de novo TG synthesis in the liver (VLDL), intestinal absorption of dietary fats (chylomicrons), lipolysis in the peripheral circulation (mediated mostly by LPL), and hepatic clearance." (PMID 35750212, 2022). "We conclude that ANGPTL8 is specific for the regulation of TG-rich lipoproteins through the LPL pathway and that therapeutically targeting ANGPTL8 for the treatment of hypertriglyceridemia or cardiovascular disease may have different outcomes than targeting ANGPTL3." (PMID 34461133, 2021). "However, ddY mice are known to possess higher LPL activities and have the potential to induce lipid-induced hypertriglyceridemia; however, they are not often selected for OLTT studies." (PMID 33022003, 2020). "Retroviral delivery of hLPL is not a viable treatment for human hypertriglyceridemia, but these experiments demonstrate that long-term expression of hLPL in skeletal muscle will likely reduce or even eliminate hypertriglyceridemia wherein total absence of LPL is not present." (PMID 29304082, 2018). "However, both an excess and a lack of APO-CII inhibit LPL activity and thus result in hypertriglyceridemia." (PMID 29270132, 2017).
hypertriglyceridemia (continued). "Since pregnancy can exacerbate hypertriglyceridemia in the genetic absence of lipoprotein lipase, a further reduction of dietary fat intake to < 1–2% of total caloric intake may be required during the pregnancy, along with the administration of a fibrate." (PMID 15610556, 2004). "Hypertriglyceridemia might have involved no change in apoB100 turnover, which would have suggested altered plasma lipid turnover without a change in particle metabolism (e.g., a lipoprotein lipase or ApoCIII effect)." (PMID 36737040, 2023). "In 2012, we found an excessive prevalence of rare variants in LPL, APOC2, GPIHBP1, APOA5, and LMF1 in patients with severe hypertriglyceridemia, again indicating that heterozygosity was a predisposing factor for, although not an absolute cause of severe hypertriglyceridemia or MCM." (PMID 32793115, 2020). "By contrast, Olivecrona found that the induction of adipose tissue LPL activity with feeding was similar in type 2 diabetes patients and matched healthy controls, suggesting that dysregulation of adipose LPL is not involved in the postprandial hypertriglyceridaemia in type 2 diabetes." (PMID 32504883, 2020). "A previous study has shown that a decrease in LPL activity may result in the reduced decomposition of TG-rich VLDL and CM, slow clearance rate, increased plasma TG levels, and inhibited HDL-C formation, thus leading to hypertriglyceridemia, low HDL-C level and, ultimately, obesity." (PMID 31284674, 2019). "Consequently, the lack of changes in insulin concentration during fructose intake does not affect lipoprotein lipase activity, which may lead to hypertriglyceridemia." (PMID 31684199, 2019). "Under normal conditions, insulin activates the enzyme lipoprotein lipase (LPL), but if insulin is not present, LPL is not activated, resulting in hyperglyceridemia and hypercholesterolemia." (PMID 29048380, 2017). "Primary lipoprotein lipase (LPL) deficiency is a rare autosomal recessive disorder characterized by severe hypertriglyceridemia, due to the accumulation in plasma of chylomicrons and very low density lipoproteins (VLDL) that result from the absence of LPL activity." (PMID 15610556, 2004). "Interestingly, in mice, FGF21 knockdown via short hairpin RNA contributed to hypertriglyceridemia that was not exacerbated by pharmacological inhibition of LPL, suggesting FGF21 may positively regulate peripheral LPL activity." (PMID 35629964, 2022). "LPL release from endothelial cells in response to heparin stimulation requires the activity of GPIHBP1 (GPI-anchored high-density lipoprotein binding protein 1) and primary genetic defects in this GPI-anchored protein lead to hypertriglyceridemia and non-detectable serum lipoprotein lipase." (PMID 25885527, 2015).
Insulin resistance (270 papers, 2007 to 2026). Increased resistance towards insulin, that is, diminished effectiveness of insulin in reducing blood glucose levels. "The protein impairs glucose tolerance, increases insulin resistance, increases the risk of cardiovascular disease, and accelerates atherosclerosis by decreasing lipoprotein lipase expression, increasing plasma triglyceride concentration." (PMID 39919333, 2025). "Second, the study-design precludes examination of causality for the relationship between insulin resistance and LPL, HTGL, and GPIHBP1." (PMID 40507147, 2025). "The −93 T< G promoter gene polymorphism of LPL, a rare variant, has been found to be associated with obesity, while the rare variant −53 G<C is associated with insulin resistance." (PMID 39590382, 2024). "The same researchers evaluated ec-SOD levels with an ELISA method in patients undergoing haemodialysis, describing a correlation between the enzyme, FFA, and LPL, underlying the role of insulin resistance." (PMID 38275651, 2024). "Muscle lipoprotein lipase has been associated with insulin resistance, as has accumulation of lipids inside muscle cells." (PMID 38753649, 2024). "Elevated levels of LPL have been linked to an increase in triglycerides, which can ultimately result in the accumulation of lipids, lipotoxicity, and insulin resistance." (PMID 39409049, 2024). "Overall, fibrate use is associated with reduced hepatic and extra-hepatic tissue insulin resistance and with the upregulation of the lipoprotein lipase, a key enzyme in the pathogenesis of hepatic steatosis." (PMID 36983739, 2023). "On the other hand, LPL deficiency causes impaired glucose tolerance, insulin resistance, and increased lipid levels." (PMID 37432202, 2023). "Improving insulin resistance is also directly linked to increased lipoprotein lipase (LPL) expression." (PMID 37371552, 2023). "Mice with overexpressed LPL in their skeletal muscles accumulate TG in their muscles, which, in turn, causes insulin resistance." (PMID 37432202, 2023). "In particular, insulin resistance or insulin deficiency in patients with T2D can affect triglyceride levels through altered lipoprotein lipase function, which has likelihood of decrease accuracy of FLI." (PMID 38153732, 2023). "Insulin resistance creates a relative insulin deficiency that downregulates the enzyme lipoprotein lipase (LPL) which metabolizes triglyceride(TG) molecules." (PMID 36992741, 2022). "The relative insulin deficiency or insulin resistance and the decrease in adiponectin level cause a decrease in the activity of lipoprotein lipase enzyme resulting in high levels of LDL, total cholesterol, triglycerides, and low levels of HDL." (PMID 36424970, 2022). "In the hypothalamus, LRP1–/– mice exhibit obesity associated with hyperlipidemia, glucose intolerance, and insulin resistance, with similar phenotypes observed in neuronal LPL-deficient mice." (PMID 36590920, 2022). "Insulin resistance caused by prolactin located in the human placenta introduces recession of the LPL activity and improved lipolysis of the adipose tissue." (PMID 35126125, 2021). "Enhanced visceral fat lipolysis by adipose tissue lipoprotein lipase triggers the production of excessive free fatty acids, causing insulin resistance and metabolic diseases." (PMID 34960109, 2021). "Insulin resistance cause impaired glycogen synthesis and protein catabolism in skeletal muscles and inhibit lipoprotein lipase activity in adipocytes leading to an increased release of free fatty acids and inflammatory cytokines such as IL-6, TNFα, and leptin." (PMID 30170598, 2018). "And the decreased LPL activity has been identified to be caused by secondary hyperparathyroidism induced insulin resistance (IR) and excess of lipase inhibitors like apolipoprotein (Apo) C-III in the progression of CKD." (PMID 30359237, 2018). "Previous studies reported that LPL variants are associated with individual components of MetS, as well as with insulin resistance and CVD." (PMID 27386434, 2016).
Insulin resistance (continued). "For instance, mice with targeted overexpression of lipoprotein lipase (LPL) in the liver develop liver-specific steatosis associated with liver-specific hepatic insulin resistance." (PMID 24264040, 2013). "Although dyslipidemia is associated with insulin resistance (IR) and type 2 diabetes (T2D), there are limited data available regarding the relationship of LPL and 25(OH)D to IR and T2D at a population level." (PMID 23320821, 2013). "Taken together with our findings, the presence of detectable HIV-RNA under ART may be associated with increased accumulation of visceral fat, insulin resistance, and IL-6 and decreased mRNA expression of LPL in adipose tissue." (PMID 41156460, 2025). "In addition, normal insulin-mediated lipoprotein lipase activation is diminished in insulin resistance where patients are relatively insulin deficient and particularly in those with poor glycemic control." (PMID 38846018, 2024). "These alterations reduce muscle oxidative capacity while at the same time increasing anaerobic and glycolytic capacities and are responsible for metabolic dysfunction since they cause microinflammation, insulin resistance, and a decrease in the expression/activity of muscle LPL." (PMID 38674801, 2024). "Elevated plasma TGs are associated with insulin resistance and chronic inflammation, and may be caused by decreased plasma clearance from suppressed LPL activity." (PMID 36208911, 2023). "Moreover, endocannabinoids can activate lipoprotein lipase, promote adipogenesis and fat deposition, and cause insulin resistance in adipose tissue and skeletal muscle." (PMID 36600288, 2023). "Since insulin activates LPL, a ‘relative’ insulin deficit and/or insulin resistance in type 2 diabetes may be the cause of decreased LPL activity." (PMID 38303975, 2023). "Insulin resistance usually associates with metabolic syndrome and type-2 diabetes, and by downregulating the enzymatic activity of lipoprotein lipase it affects the levels of circulating lipoproteins towards a profile characterized by increased triglycerides and decreased HDL-cholesterol." (PMID 35818956, 2022). "Moreover, the interaction between miR-467b and LPL gene expression was associated with insulin resistance, a major cause of NAFLD (Hepatocyte)." (PMID 34072137, 2021). "Following acute insulin resistance or moderate hypoinsulinemia and hyperglycemia in rats, LPL is “switched on”, causing a robust expansion of heparin-releasable coronary LPL." (PMID 34356640, 2021). "Moreover, protein deficiency can induce insulin resistance associated with reduced LPL activity, overproduction of TAG, and impaired VLDL catabolism." (PMID 33540612, 2021). "Since insulin is an activator of LPL, it has been suggested that the diminution of LPL activity may be due to a relative insulin deficiency and/or insulin resistance." (PMID 25725623, 2015). "Moderately increased IL-6 levels seen in obese individuals may contribute to the development of obesity-associated complications, e.g., insulin resistance, via the inhibition of lipoprotein lipase activity in the adipose tissue." (PMID 26516848, 2015). "The underlying insulin resistance may impair the activity of lipoprotein lipase leading to decreased catabolism of triglyceride-rich Apo B lipoproteins." (PMID 24818163, 2014). "Notably, overexpression of human LPL in mouse skeletal muscle is associated with insulin resistance." (PMID 24086538, 2013). "In addition to its effect on the lipid metabolism, LPL is also directly or indirectly implicated in some pathophysiological conditions such as insulin resistance (IR) and type 2 diabetes (T2D)." (PMID 23320821, 2013). "Two possible mechanisms explaining the increased level of RLP-TG could be presented, one is the decreased metabolism of TG caused by decreased LPL activity induced by insulin resistance and another is the overproduction of TG." (PMID 23671852, 2013).
Insulin resistance (continued). "Since LPL provides fatty acids to the tissues and fatty acids evoke insulin resistance, LPL gene deficiency could affect glucose metabolism." (PMID 22028972, 2012). "Reduced lipoprotein lipase activity, impaired triglyceride clearance, and chronic inflammation result in a distinct dyslipidemia profile, which may weaken the association between TyG and insulin resistance compared to the general population." (PMID 40764800, 2025). "Activation of PPAR-γ is associated with preferential LPL-mediated fatty acid storage in adipose tissue through transcriptional control of this lipase, whereas some abnormalities in lipoprotein metabolism that cause insulin resistance decrease both PPAR-γ and LPL." (PMID 37108229, 2023). "Moreover, overexpression of LPL can cause insulin resistance and obesity." (PMID 35204193, 2022). "This fact could be justified due to the absence of the action of VITD metabolites that increase the expression of lipoprotein lipase in vitro, as well as the increased number of patients with peripheral insulin resistance in this group, which may cause a decrease in triglyceride levels." (PMID 34578857, 2021). "In addition, insulin resistance has been associated with increased production of intestinal lipoproteins in the postprandial state, and has also been associated with decreased muscle lipoprotein lipase activity." (PMID 33308235, 2020). "This could be due to the diminished LPL activity in adipose tissue caused by insulin resistance." (PMID 27686975, 2016). "In particular, individuals with a greater insulin resistance present with a lower LPL level and a higher HTGL level." (PMID 40507147, 2025). "In this study, we investigated the metabolic characteristics of PLH, focusing on LPL, body composition, and the relationship of LPL with lipid abnormalities, insulin resistance, and treatment necessity." (PMID 41156460, 2025). "Adiponectin is an inducer of LPL secretion and has been reported to be a factor reflecting insulin resistance." (PMID 40507147, 2025). "Insulin resistance increases the activity of hormone-sensitive lipase in adipose tissue while diminishing the activity of lipoprotein lipase." (PMID 40541990, 2025). "We have reported that insulin resistance leads to a decrease in LPL and an increase in GPIHBP1 levels." (PMID 41156460, 2025). "Insulin resistance also reduces the activity of lipoprotein lipase, a key mediator of VLDL clearance." (PMID 40161019, 2025). "In T2D, this leads to reduced LPL activity and ensuing lipotoxicity, characterized by increased deposition of lipids within tissues, including cardiac tissue, further enhancing insulin resistance and promoting CVD." (PMID 41373652, 2025). "Insulin resistance also decreases lipoprotein lipase activity, a major mediator of VLDL clearance, and it has been strongly correlated with insulin resistance." (PMID 40005397, 2025). "Under diabetic conditions, insulin resistance disrupts this pathway, leading to altered PPARγ activity and, consequently, LPL dysregulation." (PMID 41373652, 2025). "Higher fasting insulin levels attributed to increased insulin resistance were correlated with lower LPL levels in the peripheral bloodstream among participants classified as NGT." (PMID 40507147, 2025). "We propose that insulin resistance-induced LPL dysregulation is a key driver of the observed metabolomic perturbations through three primary pathways." (PMID 41373652, 2025). "Circulating GPIHBP1 levels are affected in a compensatory manner in response to a decrease in circulating LPL levels correlated with insulin resistance." (PMID 40507147, 2025). "Glycemic control was critical through both pregnancies as insulin resistance can disrupt lipid metabolism, leading to increased production and reduced clearance of TGs, and a decrease in LpL activity." (PMID 39949380, 2025).